TMEM106A (transmembrane protein 106A)
Diseases named in the same sentence as TMEM106A in open-access papers (continued):
Sharing a sentence is not in itself a finding about the gene and the disease.
tumor (10 papers, 2014 to 2025). "Spatial mapping localizes TMEM106A to peri‐necrotic and microvascular regions, niches that accumulate tumor‐associated macrophages (TAMs) in GBM and align with IL‐6–enriched inflammation." (PMID 41354084, 2025). "According to previous literature, scholars have identified that TMEM106A loss is enhanced in many cancer types and inhibits tumor cell proliferation and invasion, suggesting a suppressive role." (PMID 41354084, 2025). "TMEM106A also tended to correlate negatively with populations enriched for stem‐like tumor characteristics, indicating a closer association with inflammatory/reactive microenvironments than with tumor stemness." (PMID 41354084, 2025). "For risk prediction, incorporating TMEM106A levels (tumor RNA‐seq or IHC) into integrative models can refine clinical decision‐making." (PMID 41354084, 2025). "Simultaneously, the identification of EPITHELIAL_MESENCHYMAL_TRANSITION (EMT) and KRAS_SIGNALING_UP highlights TMEM106A‐linked molecular events that are often implicated in tumor invasiveness and metastatic potential." (PMID 41354084, 2025). "We hypothesized that TMEM106A expression associates with tumor aggressiveness and may serve as a prognostic, microenvironmental biomarker." (PMID 41354084, 2025). "In this study, we found that TMEM106A hypermethylation is associated with tumor size." (PMID 35713314, 2022). "TMEM106A promoter methylation was significantly associated only with smoking and tumour metastasis." (PMID 24975047, 2014). "These techniques enabled us to examine how TMEM106A expression varies across distinct histologic regions, from the relatively less malignant leading edge to the highly proliferative and necrotic tumor core." (PMID 41354084, 2025). "We observed a clear spatial gradient in TMEM106A levels, with higher expression concentrated in peri‐necrotic zones and densely cellular tumor areas, while comparatively lower expression was noted at the tumor edge and necrotic regions." (PMID 41354084, 2025). "The prominence of these pathways suggests that high TMEM106A expression is closely tied to a more hostile tumor microenvironment characterized by enhanced inflammation and immune cell infiltration." (PMID 41354084, 2025). "In particular, tumor-specific DNA methylation of TMEM106A is frequently observed in tumor tissues from HCC patients." (PMID 35713314, 2022). "MSP assays showed that TMEM106A was methylated in 55% (33/60) of tumor tissues and 23.3% (14/60) of peri-tumor tissues (P<0.001)." (PMID 35713314, 2022). "Since overexpression of TMEM106A in HCC cells significantly inhibited cell migration and invasion, we established a tumor xenograft model to explore the effect of TMEM106A on HCC growth and metastasisin vivo." (PMID 35713314, 2022). "TMEM106A mRNA expression in tumor tissues was significantly decreased compared with that in peri-tumor tissues." (PMID 35713314, 2022). "Some evidence has implied that TMEM106A is involved in the suppression of tumor cell proliferation and migration by apoptosis induction." (PMID 35713314, 2022). "Comprehensive and integrative genomic HCC studies have found that TMEM106A has high levels of tumor-specific methylation accompanied by decreased RNA expression." (PMID 35713314, 2022). "TMEM106A methylation and mRNA expression were examined in tumors and corresponding paired peri-tumor tissues of 60 HCC patients." (PMID 35713314, 2022). "In summary, we demonstrate that tumor-specific methylation of TMEM106A frequently occurs in HCC and that such methylation plays an important role in the transcriptional regulation of TMEM106A." (PMID 35713314, 2022). "Taken together, these results demonstrate that TMEM106A is a novel anti-oncogene involved in the inhibition of tumor growth and progression." (PMID 35713314, 2022). "TMEM106A protein expression was undetectable in 23% of patients, with low levels of staining in 53% of the tumor tissues." (PMID 35713314, 2022).
tumor (continued). "Moderate or intense TMEM106A staining was observed in 17% and 7% of the tumor tissues, respectively." (PMID 35713314, 2022). "By comparison of the ratio of paired tumor to peri-tumor tissue, TMEM106A had a greater level of methylation in HCC tumor tissues of 83% of patients (ratio≥1.5)." (PMID 35713314, 2022). "Restoration of TMEM106A expression induced GC cell apoptosis and suppressed GC cell growth, suggesting that TMEM106A is a tumor suppressor in GC14." (PMID 26215746, 2015). "Immunohistochemistry was performed to evaluate TMEM106A protein expression in 49 paired GCs and their cancer adjacent non-tumour tissues." (PMID 24975047, 2014). "Restoration of TMEM106A expression induced GC cell apoptosis and suppressed GC cell growth, suggesting that TMEM106A is a tumour suppressor in GC." (PMID 24975047, 2014). "Further analysis suggested that TMEM106A methylation in primary GCs was significantly correlated with smoking and tumour metastasis." (PMID 24975047, 2014). "By comparison with non-tumour stomach, the levels of TMEM106A mRNA in detected GC cell lines were significantly decreased." (PMID 24975047, 2014). "If TMEM106A is indeed a tumour suppressor, inactivation of the gene by promoter methylation would favour tumour progression and a worse outcome." (PMID 24975047, 2014). "Frequent methylation of TMEM106A was detected in GCs (93/105, 88.6%), while only two cases were methylated among 11 cancer adjacent non-tumour samples (2/11, 18.1%)." (PMID 24975047, 2014). "Using real-time quantitative PCR, we detected the levels of TMEM106A mRNA in eight GC cell lines and non-tumour stomach tissue." (PMID 24975047, 2014). "Further analysis suggested that TMEM106A methylation in primary GCs was significantly correlated with smoking (P = 0.0422), and tumour metastasis (P = 0.0462)." (PMID 24975047, 2014). "The molecular basis of TMEM106A's tumour suppressor property in GC involved activation of the caspase cascade, partly mediated the enhanced apoptosis ability by TMEM106A and subsequent cleavage of substrates." (PMID 24975047, 2014). "Our nomogram —combining TMEM106A with gender, chemotherapy, age, Karnofsky performance score, tumor grade, and radiotherapy—illustrates individualized survival estimation and could guide treatment intensity or surveillance frequency." (PMID 41354084, 2025). "We then visualized TMEM106A expression using color gradients from yellow (low) to red (high), revealing that numerous myeloid cells showed relatively high TMEM106A levels, followed by T‐cell clusters, whereas the tumor and glial compartments generally exhibited lower expression." (PMID 41354084, 2025). "Quantitative comparisons revealed that TMEM106A showed a trend of being slightly upregulated in the cellular tumor compartment compared to the leading edge, with further increases observed in microvascular proliferation and only a slight decrease in the pseudopalisading cells surrounding necrosis." (PMID 41354084, 2025). "Next, we investigated the relationship between TMEM106A and tumor grade." (PMID 41354084, 2025). "Finally, the molecular mechanisms by which TMEM106A inhibits HCC tumor growth, invasion, and metastasis are explored by downregulation or overexpression of TMEM106A in HCC cell lines." (PMID 35713314, 2022). "The cellular function of TMEM106A is not very clear, although it is implicated as a tumor suppressor in some cancers." (PMID 35198896, 2022). "In addition, we examine tumor-specific methylation and RNA expression of TMEM106A in a cohort of HCC patients with respect to clinico-pathologic patient characteristics and prognosis." (PMID 35713314, 2022). "We proposed that TMEM106A is a novel functional tumor suppressor in gastric carcinogenesis." (PMID 26215746, 2015). "This anti-tumour effect of TMEM106A in GC suggests that restoration of the function of TMEM106A could halt or reverse GC, thus having a potential therapeutic effect." (PMID 24975047, 2014).
tumor (continued). "TMEM106A is a novel functional tumour suppressor in gastric carcinogenesis." (PMID 24975047, 2014). "TMEM106A is a candidate tumour suppressor, and TMEM106A methylation may serve as an epigenetic biomarker in GC." (PMID 24975047, 2014). "Thus, the in vitro and in vivo results indicated that TMEM106A functions as a tumour suppressor in gastric carcinogenesis." (PMID 24975047, 2014). "Furthermore, TMEM106A methylation was significantly correlated with tumor size (P=0.008)." (PMID 35713314, 2022). "Thus, TMEM106A inhibits the growth of GC cells, functioning as a potential tumour suppressor." (PMID 24975047, 2014). "Therefore, TMEM106A tumour-specific promoter methylation may become an epigenetic biomarker for GC." (PMID 24975047, 2014). "Other clinico-pathological parameters such as age, tumor number, preoperative serum alpha-fetoprotein, vascular invasion, and tumor differentiation were not correlated with TMEM106A methylation." (PMID 35713314, 2022). "Clinically, TMEM106A methylation can discriminate tumor tissues from non-malignant adjacent tissues of HCC patients." (PMID 35713314, 2022). "Receiver operating characteristic (ROC) curve analysis reveals that methylation of TMEM106A in tumor samples is different from that in non-malignant adjacent tissues of HCC patients." (PMID 35713314, 2022). "Multivariate analysis indicated that TMEM106A expression is an independent predictor of OS and PFS (hazard ratio 0.541,P<0.01; and hazard ratio 0.658, respectively,P<0.05), as well as tumor size, tumor number, and tumor differentiation." (PMID 35713314, 2022). "Receiver operating characteristic (ROC) curve analysis revealed TMEM106A methylation in tumor samples was different from that in non-malignantadjacent tissues of HCC patients (P<0.01; AUC=0.731)." (PMID 35713314, 2022). "The expression of TMEM106A protein was positive (45/49, 91.8%) in most cancer adjacent non-tumour tissues, but was near negative (48/49, 98.0%) in primary GCs." (PMID 24975047, 2014). "Compared with Ad5-null and mock group, there was no visible tumour in the Ad5-TMEM106A group, indicating TMEM106A inhibits tumourigenicity." (PMID 24975047, 2014). "The frequent silencing of TMEM106A in GC cell lines and primary cancers, but not in normal gastric mucosa, suggested that TMEM106A is a tumour suppressor." (PMID 24975047, 2014). "Our results suggested that TMEM106A expression was reduced or absent in most tumour cell lines." (PMID 24975047, 2014). "However, TMEM106A hypermethylation is not related to vascular invasion, differentiation, or TNM stage of the tumor." (PMID 35713314, 2022).
cancer (8 papers, 2014 to 2026). A tumor composed of atypical neoplastic, often pleomorphic cells that invade other tissues. "A summary of TMEM106A's known mechanisms across cancers is provided in to underscore this dualistic behavior." (PMID 41354084, 2025). "Expression of transmembrane protein 106A (TMEM106A) has been reported to be dysregulated in several types of cancers." (PMID 35713314, 2022). "TMEM106A was methylated in 88.6% (93/105) of primary GC and 18.1% (2/11) in cancer adjacent normal tissue samples." (PMID 24975047, 2014). "TMEM106A induces cancer cell apoptosis through caspase-2/BID activation and the mitochondrial pathway." (PMID 24975047, 2014). "TMEM106A inhibits cancer cell proliferation and migration by inducing apoptosis." (PMID 35198896, 2022). "We showed that the silencing or down-regulation of TMEM106A was closely related with promoter hypermethylation, as demonstrated by methylation-specific PCR, BGS analysis and by the restored expression of TMEM106A in silenced cancer cells obtained using 5-Aza treatment." (PMID 24975047, 2014). "Gene therapy is one of the approaches for inducing cancer cell apoptosis, and TMEM106A may show its pro-apoptotic effect in specific and combinatorial treatment approaches in the future." (PMID 24975047, 2014).
infection (1 paper, 2022). The state of being infected such as from the introduction of a foreign agent such as serum, vaccine, antigenic substance or organism. "Based on these results, we hypothesized a working model for the inhibition of EV-A71 infection by TMEM106A." (PMID 35359978, 2022). "In contrast, CV-A10 infection was not affected by TMEM106A expression." (PMID 35359978, 2022). "TMEM106A blocks SCARB2-mediated EV-A71 and CV-A16 infection but does not affect infections mediated by other receptors." (PMID 35359978, 2022).
TMEM106A also shares sentences with these, for which no sentence is quoted: breast tumor (1 paper); immune diseases (1); kidney cancer (1); liver cancer (1); memory impairment (1); neuroblastoma (1); oligodendroglioma (1); prostate carcinoma (1); Stroke (1); Uterine leiomyoma (1).